IL6 (interleukin 6)
Diseases named in the same sentence as IL6 in open-access papers (continued):
Sharing a sentence is not in itself a finding about the gene and the disease.
atherosclerosis (continued). "IL-1β, IL-6, and TNF-α are soluble low-molecular-weight-proteins that mediate crosstalk between immune and nonimmune cells and have been implicated in atherosclerosis development and progression." (PMID 32485823, 2020). "Importantly, IL-6 and MCP-1 are thought to play essential roles in vascular inflammation and in the initiation and progression of atherosclerosis." (PMID 32221618, 2020). "Moreover, ruxolitinib remarkably decreased plasma levels of IL-6, IL-1β, IFN-γ and TNF-α in rabbits with atherosclerosis." (PMID 32169038, 2020). "Similarly, Decitabine treatment downregulated the expression of inflammation genes, TNF-α, IL-6, and IL-1β, and the chemotaxis gene MCP-1 resulting in the amelioration of atherosclerosis." (PMID 32714333, 2020). "Taking into account our results, we hypothesized that the high level of plasma lipids, increased the secretion of IL-6, IFN-γ and TNF-α, subsequently activating JAK2/STAT3 to induce and aggravate atherosclerosis." (PMID 32169038, 2020). "CoQ10 could also inhibit the inflammatory proteins such as IL-6, TNF-α, ICAM-1, VCAM-1 and NLRP3, thus exerting the role inhibiting atherosclerosis." (PMID 32792941, 2020). "The results showed that rabbits with atherosclerosis presented higher IL-6, IL-1β, IFN-γ and TNF-α levels than those in the control group; however, ruxolitinib substantially decreased IL-6, IL-1β, IFN-γ and TNF-α contents in rabbits with atherosclerosis." (PMID 32169038, 2020). "This study has shown that attenuation of cardiac remodeling, fibrosis, alleviation of the aortic root and coronary arteries atherosclerosis is dependent on the reduction of IL-1β, TNF-α, IL-6 cardiac mRNA expression, and nuclear factor kappa B (NF-κB) activation pathway in RVX pre-treated group." (PMID 33301454, 2020). "In this study, the direct inhibition of CCL4 could decrease circulating IL-6 and TNF-α levels, suggesting the potential modulation of downstream inflammatory cytokines by blocking CCL4 in atherosclerosis in vivo." (PMID 32911750, 2020). "Therefore, inflammatory mediators such as interleukin (IL)-6, IL-8, and tumor necrosis factor-α (TNF-α) are commonly involved in the pathogenesis of RA-related atherosclerosis." (PMID 32824307, 2020). "Cytokine IL-6, TNF-α, and MCP-1 promote atherosclerosis and are classified as pro- cytokines, while cytokine IL-10 and TGF-β suppress the formation and progression of atherosclerosis and are categorized as anti-atherogenic cytokines." (PMID 32611832, 2020). "In a multivariate analysis, the prognostic value was independent of the other inflammatory biomarkers (IL-6, CRP) and classical risk factors of atherosclerosis." (PMID 31687090, 2019). "Although, embelin has been reported to inhibit IL6/STAT3 and NF-κB signaling pathways, whether embelin can utilize these properties to prevent the progression of atherosclerosis also needs to be further clarified." (PMID 31635287, 2019). "Among cells involved in the early steps of atherosclerosis, monocyte-derived dendritic cells (Mo-DCs) respond to inflammatory stimuli, including platelet-activating factor (PAF), by the induction of various cytokines, such as interleukin 6 (IL-6)." (PMID 31289638, 2019). "This leads to the release of an array of pro-inflammatory cytokines, such as interleukin-1-alpha (IL-1α), IL-1β, IL-6, tumor necrosis factor-alpha (TNF-α) and matrix metalloproteinases (MMPs), which further exacerbates atherosclerosis by promoting immune cell infiltration." (PMID 31357404, 2019). "IL-1β, IL-6, IL-8, and MCP-1 are important factors in the development of atherosclerosis." (PMID 31452653, 2019). "Other clinical parameters of atherosclerosis or cardiac function in patients with early onset CAD did not correlate with IL-6 level." (PMID 31739518, 2019).
atherosclerosis (continued). "We therefore suggest that macitentan treatment is able to improve endothelial function and reduce inflammatory mediators such as IL-6, but this did not translate through to reduced atherosclerosis in our study setting." (PMID 29261014, 2018). "IL‐6 may play a pivotal role in EREG upregulation by IH and consequently OSA‐related atherosclerosis." (PMID 29744301, 2018). "Endothelial activation, characterized by excessive cytokines (IL-6 and IL-8) production and adhesion molecules (ICAM-1 and VCAM-1) expression, is a crucial factor in the development of atherosclerosis and SCFA regulated endothelial activation in different ways." (PMID 29615908, 2018). "This study demonstrated a detrimental role of TLR7 in diet-induced atherosclerosis in Apoe−/− mice by increasing lesion inflammation (MHC-II), lesion pro-inflammatory cytokine expression (IL6), lesion protease expression (CatS, and MMP-9), and systemic inflammation (plasma SAA)." (PMID 28405010, 2017). "Furthermore, the p38 pathway is implicated in cholesterol ester accumulation in MΦ and the development of atherosclerosis, since its activation plays an essential role in the production of inflammatory cytokines (TNF-α, IL-6)." (PMID 28173800, 2017). "Hansson describes, for example, the development of an inflammatory cascade in atherosclerosis, involving, but not limited to, inflammatory cytokines (e.g. tumor necrosis factor alpha (TNF-α), interleukin-1 (Il-1)), interleukin-6 (Il-6), and acute-phase reactants (e.g. C-reactive protein (CRP))." (PMID 27270459, 2016). "For instance, we reported that ApoE null mice exposed to ambient UFP for 5 weeks, exhibited proinflammatory HDL and enhanced atherosclerosis, at the same time when there were no significant changes in plasma levels of IL-6 and IL-8 (unpublished)." (PMID 27221567, 2016). "Among them, some research has shown that IL-6 in inflammatory response may mediate artery atherosclerotic plaque vulnerability and burst, and TNF-α may promote atherosclerosis formation." (PMID 27563892, 2016). "In rabbits with induced atherosclerosis and chronic arthritis, treatment with G inhibited NF-κB activation and down-regulated COX-2 expression in peripheral blood mononuclear cells, while also decreasing circulating levels of CRP and IL-6." (PMID 25719429, 2015). "Based on the effects of IL-6 and TNF-α in inflammatory reaction and atherosclerosis, the role of CCC in preventing atherosclerosis may be related to inhibiting the inflammation reaction." (PMID 26539229, 2015). "Additionally, because high glucose (HG) increases IL6 only in Steap4-deficient [but not wild-type (WT)] adipocytes 14 while overexpressing Steap4 suppresses atherosclerosis in diabetic mice 18, we hypothesize that Steap4 overexpression may attenuate HG or S100B-induced effects in mesangial cells." (PMID 25817898, 2015). "The included studies used different blood-derived markers of atherosclerosis, such as: high sensitivity CRP (hsCRP), vasogenic endothelial growth factor (VEGF), interleukins (IL) IL-6 and IL-18, osteopontin (OPN), osteoprotegerin (OPG) and tumor necrosis factor-alpha (TNF-α)." (PMID 25984600, 2015). "Increased plasma concentrations of TNF-α, IL-6, FFA, and PAI-1 and decreased concentrations of adiponectin may lead to accelerated atherosclerosis, plaque instability, and arterial thrombosis." (PMID 25935836, 2015). "In addition, the inflammatory factors, such as IL-6, TNF-α, significantly contribute to the development, progression and destabilization of atherosclerotic plaques; production of fibrinogen might be enhanced by inflammatory process associated with atherosclerosis." (PMID 26283889, 2015). "In addition, some studies have shown a correlation between subclinical atherosclerosis and selected proinflammatory factors such as C-reactive protein (CRP), fibrinogen, tumor necrosis factor-α (TNF-α), and interleukin-6 (IL-6)." (PMID 24772446, 2014).
atherosclerosis (continued). "Meanwhile, the expressions of IL-6, TNF-α, MCP-1 and VCAM-1 were up-regulated in apoE-/- mice treated with salusin-β, indicating that salusin-β could aggravate the progression of atherosclerosis via up-regulation of inflammatory molecules." (PMID 24621517, 2014). "In fact, previous studies have reported that some components of the MD such as EVOO or nuts may down-regulate inflammatory markers related to atherosclerosis such as VCAM-1, ICAM-1, E- and P-Selectin, CRP and IL-6." (PMID 24925270, 2014). "Although SMC activation clearly participates in atherosclerosis, in our in vitro studies here the levels of MCP-1, IL-6, VEGF, and IL-8 protein detected in the supernatants of HAoAFs were similar or higher on a cell/cell basis than those detected in HAoSMC supernatants." (PMID 24307759, 2013). "After the atherosclerosis model was established, the level of the serum lipids, hs CRP and IL-6 of rabbits in high-cholesterol group and Losartan group increased significantly in comparison with control group(P < 0.05), but there was no statistical difference between the two groups (P > 0.05)." (PMID 25478508, 2013). "IgG antibodies against herpesviruses, carotid intima-media thickness (cIMT), endothelial function through flow-mediated dilatation (FMD) of the brachial artery, and blood atherosclerosis biomarkers (hsCRP, TNF-α, IL-6, MCP-1, MDA, sCD14, sCD163, VCAM-1, ICAM-1, D-dimer, and PAI-1) were measured." (PMID 23717597, 2013). "Neutralization of IL-17A not only reduced the atherosclerotic plaques but also down regulated IL-6, TNF-α and CCL5 that suggests that regulation of these cytokines may be interconnected in atherosclerosis." (PMID 23437105, 2013). "Therefore, significant reduction in percentage of CD11b, IL‐6, TUNEL, or APG5L/ATG cells, which are in particular seen after 20 weeks of CED, seem to be responsible for the inhibition of atherosclerosis progression after 20 weeks of CED." (PMID 23316317, 2012). "Finally, IL-6, a metabolic syndrome and atherosclerosis-related inflammatory marker could be of value in clinical practice as an indicator (together with HgbA1c) of the efficacy of the treatment as well as of the efficacy of preventive action on atherosclerosis." (PMID 22924123, 2012). "Atherosclerosis and CHD may be inflammatory conditions and IL-6 plays a key role in the inflammation process." (PMID 22509361, 2012). "IL-1β, IL-6 and TNF-α trigger atherogenesis by sensitizing vascular smooth muscle cells and inducing secretion of cellular adhesion molecules and matrix metalloproteinase (MMP) by monocytes during later stages of atherosclerosis." (PMID 20543948, 2010). "Among 1021 subjects, comprising 774 CAD affected members from Indian Atherosclerosis Research Study (IARS), plasma hsCRP levels showed strong correlation with inflammatory markers, namely, IL6 (r = .373; P = <.0001), sPLA2 (r = .544; P = <.0001) as also with fibrinogen (r = .579; P = <.0001)." (PMID 21152190, 2010). "Moreover, the progression of atherosclerosis seems to be more severe in patients +CAD because they presented with a higher carotid IMT, which was also correlated with higher levels of CRP, IL-6, and sVCAM-1." (PMID 19584917, 2009). "Inflammationplays a key role in mediating all stages of atherosclerosis which is considered a chronicinflammatory disease.Proinflammatory cytokines as TNF-alpha and IL-6 have both been shown to inducestructural as well as functional alterations in endothelial cells." (PMID 18437228, 2008). "Additionally, Stearoyl-CoA Desaturase 1, which is a CoA-dependent enzyme, can reduce the elevated expression of IL-6 and IL-8 induced by PA overload, and reduce endoplasmic reticulum stress, thereby mitigating VEC death and improving the progression of atherosclerosis." (PMID 41596521, 2026).
atherosclerosis (continued). "In particular, the abundance of Alistipes is negatively correlated with liver IL-17 and liver IL-6 levels, while positively correlated with serum HDL-C, indicating that dysbiosis of gut microbiota promotes endothelial inflammation and progression of atherosclerosis." (PMID 41244676, 2025). "The last but not the least, studies show that pro-inflammatory molecules such as interleukin-1, interleukin-6, and tumor necrosis factor-α both stimulate osteoclast activity, which could raise β-CTX levels, and promote atherosclerosis by triggering endothelial dysfunction and plaque inflammation." (PMID 41050279, 2025). "Furthermore, fraxin downregulated IL-6 and TNF-α expression and lowered the gene and protein levels of FAT/CD36, controlling key targets in signaling pathways related to lipid metabolism and atherosclerosis." (PMID 41458968, 2025). "Recent study elucidated its anti-angina mechanism to ameliorate atherosclerosis and stroke via exerting antioxidant and anti-inflammatory effects by counteracting the inflammation pathway and necrosis via increasing B cell/lymphoma 2 (BCL-2), lowered caspase-3 and IL-6." (PMID 41184328, 2025). "Protocatechuic acid dose-dependently inhibited the inflammation response, as evidenced by a reduction in IL-1β, IL-6, and TNF-α at the mRNA and protein levels in MLCs stimulated or unstimulated with 50 pg/mL of LPS, a reachable level in patients or laboratory animals with atherosclerosis." (PMID 40292571, 2025). "Additionally, interleukin-6 (IL-6) and high-sensitivity C reactive protein (hs-CRP), both positively correlated with serum TG levels, play roles in the shared pathophysiological mechanisms of lipid metabolism disorder and atherosclerosis." (PMID 40070586, 2025). "The main pathways involved include the focal adhesion‐PI3K‐Akt‐mTOR‐signaling pathway; AhR; fluid shear stress and atherosclerosis; protein processing in endoplasmic reticulum; thermogenesis; adipogenesis; and several inflammatory‐related pathways (IL‐5, IL‐2, TGF‐β receptor, and IL‐6 signaling)." (PMID 41169019, 2025). "While we lacked data on advanced inflammatory markers like TNF-α or IL-6, which may mediate the malnutrition-inflammation-atherosclerosis (MIA) pathway, these warrant future study." (PMID 40984946, 2025). "In addition, it did not showeffectiveness in reducing inflammation in patients with atherosclerosis—thelevels of IL-1β, IL-6 and CRP did not decrease." (PMID 40160593, 2025). "The levels of circulating pro-inflammatory cytokines, such as interleukin-1 beta (IL-1β), interleukin-6 (IL-6), and tumor necrosis factor-alpha (TNF-α), which are elevated in T2DM patients, underscore the relationship between T2DM and inflammation in the pathogenesis of atherosclerosis." (PMID 39125322, 2024). "Moreover the upregulation of certain biomarkers like OPG, RANKL, and other inflammatory cytokines like IL-6, as well as immune complex deposition, in MGUS patients may contribute to the accelerated atherosclerosis seen in these patients." (PMID 39195314, 2024). "Also, studies have found that miR‐155 could increase the expression of inflammatory factors such as IL‐6 and TNF‐α in endothelial cells, promoting atherosclerosis progression." (PMID 39495676, 2024). "Patients with type 2 diabetes (T2DM) and macrovascular atherosclerosis showed higher levels of circulating IL-6 compared to patients with atherosclerosis and no diabetes, and in combination with levels of TNFα, were better at predicting atherosclerosis development in T2DM patients." (PMID 38256155, 2024). "Specifically, interleukin‐6 (IL‐6), a prominent pro‐inflammatory cytokine, is recognized as a primary instigator of plaque destabilization, atheroprogression, and the generation of high‐sensitivity C‐reactive protein (hs‐CRP), thereby fostering the onset and progression of clinical atherosclerosis." (PMID 39669190, 2024).
atherosclerosis (continued). "Together, IL‐6 inhibition with ziltivekimab or canakinumab may prevent atherosclerosis and/or CAD independent of lipid levels and blood pressure." (PMID 38634217, 2024). "Therefore, the activation of the IL-1β/IL-6 axis by 2-AG is an interesting novel finding in vitro, but it remains unlikely to be a driver of atherosclerosis in our mouse model." (PMID 36178662, 2023). "Inflammatory modulators/biomarkers, such as IL-1α, IL-1β, IL-6, IL-12, IL-15, IL-18, and tumor necrosis factor α, or alternative anti-inflammatory cytokine IL-10, and adhesion molecules (ICAM-1, VCAM-1), involved in atherosclerosis progression have been shown to predict cardiovascular diseases." (PMID 37374202, 2023). "Prior studies have reported that some components of the MedDiet such as nuts may downregulate inflammatory markers related to atherosclerosis, such as serum C-reactive protein (CRP), interleukin 6 (IL-6), cell adhesion molecule-1 (CAM-1), and intercellular adhesion molecule-1 (ICAM-1)." (PMID 35192097, 2023). "Consistent with other systemic inflammatory diseases such as atherosclerosis, our results showed that there were obviously a variety of biomarkers that increased in these patients, including WBC, neutrophil, monocyte, PLR, NLR, hs-CRP, and IL-6, and in addition, the level of lymphocyte decreased." (PMID 37525162, 2023). "In apolipoprotein E-deficient mice model, CCL4 antibody treatment reduced circulating IL-6 and TNF-α whereby the authors concluded that CCL4 inhibition seems to be a promising tool within the box of anti-inflammatory therapeutics in patients diagnosed with atherosclerosis." (PMID 36290379, 2022). "Therefore, USF1 may be involved in atherosclerosis by regulating the expression of IL-1β, VEGF, TNF-α, and IL-6." (PMID 35783856, 2022). "IL6, CXCL8, CCL2, SOD2, NFKBIA, and BIRC3 were identified as the top 6 hub genes in the magenta module (human cardiomyocyte samples) and were mainly enriched in the NOD-like receptor signaling pathway, IL-17 signaling pathway, TNF signaling pathway, lipid and atherosclerosis signaling pathway." (PMID 36426222, 2022). "Other commercially available agents targeting IL-6 (tocilizumab), TNF-α (etanercept, adalimumab, infliximab), or IL-1 receptor antagonist (anakinra) have mostly been assessed in the setting of other inflammatory diseases and further testing in atherosclerosis is required." (PMID 36555579, 2022). "Depletion of CD8+ T cells reduced atherosclerosis, decreased the number of mature monocytes in the BM and spleen of hypercholesterolemic mice, and reduced GM-CSF and IL-6 expression in BM cells but did not affect the recruitment of monocytes to atherosclerotic plaques." (PMID 35536648, 2022). "ECD is initiated by multiple inflammatory factors in atherosclerosis; when the endothelium is injured, inflammatory mediators, including vascular cell adhesion molecule-1 (VCAM-1), intercellular adhesion molecule-1 (ICAM-1), interleukin 6 (IL-6), and tumor necrosis factor α (TNF-α)are expressed." (PMID 34899318, 2021). "Interestingly enough, in our study, DNA methylation of the IL-6 and NF-kB promoter regions and plasma miRNA-21 significantly correlated with IMT, a surrogate marker for early atherosclerosis, and MPI index, an echocardiographic parameter of cardiac dysfunction." (PMID 34869683, 2021).